RUNX1 (RUNX family transcription factor 1)
Diseases named in the same sentence as RUNX1 in open-access papers (continued):
Sharing a sentence is not in itself a finding about the gene and the disease.
Myelodysplasia (38 papers, 2008 to 2025). Clonal hematopoietic stem cell disorders characterized by dysplasia (ineffective production) in one or more hematopoietic cell lineages, leading to anemia and cytopenia. "RUNX1 was the most frequently mutated gene, with a high co-occurrence rate with other myelodysplasia-related mutations." (PMID 39201354, 2024). "Only 5 were assigned to the adverse group because of myelodysplasia-related mutations (RUNX1, n = 2; BCOR, n = 1; SF3B1, n = 1; U2AF1, n = 1)." (PMID 37085611, 2023). "Consistent with reports in adult AML, RUNX1 mutation weakly associated with the unbalanced abnormality −7/7q, which has also been described as myelodysplasia related aberration." (PMID 37188777, 2023). "Several cases of T-cell ALL have been described in patients with myelodysplasia associated with germline RUNX-1 mutation or microdeletion of 21q22 resulting in RUNX-1 deficiency." (PMID 25541649, 2014). "Presently, however, the 2022 International Consensus Classification (ICC) system categorizes AML with RUNX1 mutations under AML-myelodysplasia-related (MR), whereas the fifth edition of the World Health Organization (WHO) classification does not make this recognition." (PMID 40282530, 2025). "FLT3-ITD, NPM1, and IDH1/2 were the most mutated genes, while also high proportion of ASXL1 and RUNX1 mutations could be detected, indicating the high proportion of myelodysplasia-related AML." (PMID 39453477, 2025). "Interestingly, an inflammatory bone marrow environment and predisposition to myelodysplasia is also observed in patients with RUNX1 mutations, another key ETS transcription factor involved in megakaryopoiesis." (PMID 32841218, 2020). "In particular, the adverse-risk group has been expanded to include seven additional mutations: BCOR, EZH2, SF3B1, SRSF2, STAG2, U2AF1, and ZRSR2—together with ASXL1 and RUNX1 (already included in ELN 2017)—forming the “myelodysplasia-related” (MR) gene group." (PMID 41464583, 2025). "Concurrent TET2 and EZH2 deletion is sufficient to induce an MDS/myeloproliferative phenotype in mice, and in a RUNX1 mutant model, EZH2 loss promotes myelodysplasia development but inhibits transformation to AML." (PMID 36902450, 2023). "Mutations in the RUNX1 gene correlate with the occurrence of AML and myelodysplasia, suggesting that this TF has a tumor-suppressive function." (PMID 35399522, 2022). "Instead, 70% of IKZF1N159mut patients could be classified as "AML with myelodysplasia‐related gene mutations" (AML‐MR), mainly by a high rate of concomitant RUNX1 mutations." (PMID 40041934, 2025). "The idea that these mutations reflect myelodysplasia is reflected in the WHO-classification and the International-Consensus-Classification which – with the exemption of RUNX1 in the WHO-classification – also see these mutations as defining AML with myelodysplasia-related genetic changes." (PMID 37041198, 2023). "The list of somatically mutated genes is largely shared between the systems and includes ASXL1, BCOR, EZH2, SF3B1, SRSF2, STAG2, U2AF1, and ZRSR2. in the section on the RUNX1 mutation, this is also considered myelodysplasia-related in the ICC but not in WHO5." (PMID 37510328, 2023). "Our series encompasses a heterogeneous group of patients with different disease pathobiology with diverse genetic intricacies that may be at play (i.e., Myelodysplasia-related and post-cytotoxic therapy), possibly confounding or overriding the potential effects of RUNX1 lesions." (PMID 40282530, 2025).
Myelodysplasia (continued). "In previous 2017-edition categories of AML with myelodysplasia-related changes, AML was not otherwise specified, but AML with mutated RUNX1 experienced profound changes." (PMID 39201354, 2024).
platelet disorder (35 papers, 2016 to 2026). "RUNX1 variants detected in tumor tissue at a VAF close to 50% are potentially germline and causative of RUNX1 familial platelet disorder with associated myeloid malignancies." (PMID 40225162, 2023). "Diseases associated with RUNX1 include platelet disorders with associated myeloid malignancy and blood platelet disease." (PMID 35740337, 2022). "Heterozygous, pathogenic germline variants of RUNX1 are causative for familial platelet disorder with associated myeloid malignancies (RUNX1-FPD, FPDMM, FPD/AML; OMIM 601399; ORPHA 71290)." (PMID 33692461, 2021). "RUNX1 (MIM: 151385) encodes a transcription factor linked with a dominant platelet disorder with associated myeloid malignancy." (PMID 28669401, 2017). "Germline RUNX1 variants per se are enough to cause a platelet disorder." (PMID 40427601, 2025). "Our group previously published the generation of the RUNX1 p.Leu43Ser murine model generated by CRISPR/Cas9, reproducing the human RUNX1 p.Leu56Ser variant, to characterize the related platelet disorder." (PMID 40427601, 2025). "Familial platelet disorder with predisposition to AML (FPD/AML), caused by germline RUNX1 mutations (RUNX1-FPD), has been described in approximately 11 families." (PMID 40919141, 2025). "Unlike humans, animal models such as zebrafish and mice with heterozygous germline RUNX1 mutations do not have platelet disorders or develop AML8,9." (PMID 38890442, 2024). "Megakaryocytic differentiation is, therefore, dependent on the RUNX1/GATA1 balance as well, suggesting a likely mechanism by which these RUNX1-DBD mutants contribute to platelet disorders." (PMID 33397648, 2021). "We have investigated 41 carriers of RUNX1 alteration belonging to nine unrelated French families with FPD/AML and two syndromic patients, registered in the French network on rare platelet disorders from 2005 to 2015." (PMID 27112265, 2016).
lung cancer (33 papers, 2015 to 2025). A malignant neoplasm involving the lung. "RUNX1 mutation has been reported rarely in lung cancer, although changes in its methylation have been reported by a couple of studies." (PMID 32498288, 2020). "The association between RUNX1T1 and lung cancer is unclear, but its binding partner RUNX1 was overexpressed in non-small-cell lung cancer." (PMID 32258117, 2020). "Our study revealed that the molecular mechanism underlying NIFK-mediated CK1α downregulation in lung cancer is RUNX1-dependent at the transcriptional level." (PMID 26984280, 2016). "Moreover, downregulated expression of RUNX1 has been linked to the regulation of myeloid-derived suppressor cells in lung cancer, whereas higher levels of RUNX1 can enhance the killing effect of natural killer cells in cervical cancer." (PMID 35534796, 2022). "In this regard, we hypothesized that a regulatory network of the miR-21/RUNX1/YAP axis may be implicated in the progression of lung cancer." (PMID 33061847, 2020). "Moreover, it is indicated that after using siRUNXOR, the expression of RUNX1 is reestablished in MDSCs, and RUNX1 is negatively associated with the MDSCs proportion from patients with lung cancer." (PMID 33133086, 2020). "Therefore, the current study was conducted with the aim to verify the expected involvement of the miR-21/RUNX1/YAP axis in lung cancer, and to elucidate the underlying molecular mechanisms." (PMID 33061847, 2020). "A study showed that silencing RUNX1 inhibits lung cancer progression via the ERK/MAPK axis by modulating ACP5 expression." (PMID 39201328, 2024). "Mutations of the runt-related transcription factor 1 (RUNX1), a member of the RUNX family proteins essential for hematopoiesis, have been implicated in various solid tumors, including lung cancer." (PMID 39201328, 2024). "We evaluated the therapeutic potential of Runx1‐based MMT targeted therapy on lung cancer by daily injection of Runx1 specific inhibitor Ro5‐3335 (5 mg kg−1 i.p.)into immunocompetent mice bearing syngeneic lung cancer LLC." (PMID 37967345, 2024). "The study results show that lncRNA RUNXOR is augmented in the lung cancer blood samples, while RUNX1 activity is reversely connected with immunosuppression in MDSCs." (PMID 36817434, 2023). "proves that the RUNXOR and RUNX1 in MDSCs from the peripheral blood of lung cancer patients are differentially expressed in the tissues around the lung cancer compared to the normal tissues." (PMID 36817434, 2023). "On the other hand, among the co-downregulated transcription factors in lung cancer, we focused on RUNX1, histone deacetylase 2 (HDAC2), and peroxisome proliferator-activated receptor gamma (PPARG)." (PMID 36142846, 2022). "The beneficial effect of the therapeutic amelioration of RUNX1 in patients with nonsmall-cell lung cancer has also been described, since the RUNX1 overexpression is correlated with enhanced metastasis." (PMID 35740337, 2022). "NIFK destabilizes the transcription factor RUNX1 to enhance the metastatic ability of lung cancer cells, thereby stimulating the Wnt/β-catenin signaling pathway." (PMID 35741311, 2022). "Recently, miR-9 has been demonstrated to be inversely correlated with the expression of RUNX1 in lung cancer and miR-9 would inhibit MDSC differentiation and aggravate the suppressive function of MDSCs." (PMID 35634311, 2022). "NIFK activates TCF4/β-catenin signaling and Ki-67-dependent cell proliferation regulation through RUNX1-dependent CK1α repression and participates in the progression of lung cancer." (PMID 34712323, 2021). "We conclude that miR-21 up-regulated the YAP expression by inhibiting the transcription factor RUNX1 to regulate the immunosuppressive ability of MDSCs against lung cancer." (PMID 33061847, 2020). "Collectively, our findings demonstrated that up-regulation of miR-21 inhibits the expression of the downstream target RUNX1 in lung cancer." (PMID 33061847, 2020).
lung cancer (continued). "Meanwhile, intersection results from GeneMANIA and Cistrome highlighted YAP as the downstream target of RUNX1 in lung cancer." (PMID 33061847, 2020). "We finally compared the methylation levels of three CpGs at a CpG island of RUNX1 between our data and TCGA lung cancer data." (PMID 32498288, 2020). "As a result, our findings suggested that miR-21 can up-regulate the expression levels of YAP by targeting RUNX1 to regulate the immunosuppressive ability of MDSCs in lung cancer." (PMID 33061847, 2020). "Previous experiments in our laboratory showed that lncRNA RUNXOR accelerates MDSC-mediated immunosuppression via targeting RUNX1 in lung cancer." (PMID 31850189, 2019). "Meanwhile, we also showed that RUNX1 expression was negatively correlated with the proportion of MDSCs in the peripheral blood of lung cancer patients." (PMID 29914443, 2018). "We next used a specific siRNA to interfere with RUNXOR expression and detected the RUNX1 expression in both MDSCs from the tumor tissue of lung cancer patients and MDSCs induced from healthy donor PBMCs with GM-CSF + IL-1β." (PMID 29914443, 2018). "Here, we detected the expression of RUNX1 in the peripheral blood of lung cancer patients and found that compared with healthy controls, the RUNX1 level was decreased in lung cancer patients (P < 0.001)." (PMID 29914443, 2018). "RUNX1 has been identified as a key regulator of tumorigenesis in various epithelial cancers including breast and lung cancers." (PMID 28279210, 2017). "NIFK enhances the metastatic ability of lung cancer cells via the Runx-1-dependent repression of CK1α expression and activates TCF/β–catenin signaling, thereby promoting metastasis in lung cancer." (PMID 26984280, 2016). "RUNX1 is highly expressed in lung cancer and correlates with poor prognosis." (PMID 39201328, 2024). "The second suggests a cooperative function between RUNX2 and three transcription factors (BRCA1, FOXM1, and RUNX1) important for the specific regulation of lung cancer establishment and progression, along with three transcription factors (E2F3, FHL2, and TWIST1) of the NSCLC-GRN." (PMID 36551878, 2022). "Our results verified that RUNX1 was poorly-expressed in lung cancer tissues." (PMID 33061847, 2020). "To determine if RUNX1 hypermethylation may be a biomarker for the detection of NSCLC in other races, we tested RUNX1 hypermethylation in the 899 TCGA primary lung cancers (75 normal tissues and 824 tumor tissues)." (PMID 32498288, 2020). "The effect of RUNX1 on cell cycle in lung cancer differs between study groups." (PMID 32498288, 2020). "Consequently, these findings suggested that miR-21 can regulate YAP by regulating the expression of RUNX1 to mediate the immunosuppressive ability of MDSCs in lung cancer." (PMID 33061847, 2020). "However, a previous study reported that the knockdown of RUNX1 increased lung cancer cell growth and motility, and lung cancer patients with low RUNX1 exhibit a poor prognosis." (PMID 31795213, 2019). "In addition, RUNX1 expression was restored in MDSCs when transfected with siRUNXOR, and RUNX1 was negatively correlated with the proportion of MDSCs from lung cancer patients." (PMID 29914443, 2018). "In addition, RUNX1 expression in both the MDSCs from the tumor tissue of lung cancer patients and MDSCs induced with GM-CSF and IL-1β was decreased compared with cells of the same phenotype from adjacent tissue and PBMCs, respectively (P < 0.05)." (PMID 29914443, 2018). "In addition, as a target gene of RUNXOR, the expression of RUNX1 was downregulated in lung cancer patients." (PMID 29914443, 2018). "Our results demonstrate the prognostic value of NIFK, and suggest that NIFK is required for lung cancer progression via the RUNX1-dependent CK1α repression, which activates TCF4/β-catenin signaling in metastasis and the Ki-67-dependent regulation in cell proliferation." (PMID 26984280, 2016).
lung cancer (continued). "Importantly, by multicolor immunostaining, we confirmed that pharmaceutical systemic inhibition of Runx1 specifically blocked MMT‐driven CAF formation in the lung cancer TME, shown by a dramatic reduction of MMTs (α‐SMA+ F4/80+) in the Ro5‐3335 treated group in vivo." (PMID 37967345, 2024). "Importantly, both macrophage‐specific and systemic inhibition of Runx1 effectively blocked the tumorigenesis of lung cancer in mice; suggesting Runx1 may represent a druggable target for preventing the formation of MMT‐driven tumor‐promoting CAFs in NSCLC." (PMID 37967345, 2024). "Likewise, EBF1 and RUNX1 also appear in the LCII network, and they are also in the LCI coexpression network, probably strengthening their importance and association with the progression of some types of lung cancer." (PMID 36101460, 2022). "Thus, in this study, we aimed to determine whether RUNXOR regulates the immunosuppression of MDSCs by targeting RUNX1 in the progression of lung cancer." (PMID 29914443, 2018). "These GO terms encompass six genes relevant to lung cancer found primarily in “Pathways in cancer” GO and partially overlapping with two other GOs: FLT3, FOXO1, CSF1R, RUNX1, PPARG, and TGFBR2." (PMID 39201328, 2024). "RUNX1 is a TF identified in LCI and LCII networks, which were selected to focus the analysis on lung cancer." (PMID 36551878, 2022). "For example, miR-9 directly degrades Runx1, and miR-9 overexpression promoted MDSC function and inhibited anti-tumor immunity in a preclinical model of lung cancer." (PMID 36248881, 2022). "Thus, RUNXOR could reduce RUNX1 expression in MDSCs in vitro and in patients with lung cancer." (PMID 31404149, 2019). "In the lung cancer cohort, the NIFK and RUNX1 or CK1α RNA levels were inversely correlated, whereas the RUNX1 and CK1α RNA expression levels were positively correlated (p<0.001)." (PMID 26984280, 2016). "Co-expression network construct indicated that some of the mostly connected mRNAs and TFs were previously reported to be dysregulated in lung cancer, including SOX2, FOXF1, PTK2B, XRCC2, AML-1a (RUNX1), GATA-2 and MZF1." (PMID 26159226, 2015). "RUNX2 also acts as a coregulator of FOXM1, the TF that regulates lung cancer CCPs, and RUNX1, a TF that is coexpressed in the networks of unique lung cancer genes that are not deregulated in other lung diseases (LCI) or other types of cancer (LCII)." (PMID 36551878, 2022). "Similarly, RUNX1 is down-regulated and negatively-correlated with MDSC-mediated immunosuppression in lung cancer." (PMID 33061847, 2020). "RUNX1 stimulated G1 to S progression in hematopoietic cells, partly via transcriptional induction of cyclin D2 promoter, whereas RUNX1 depletion resulted in an increased E2F1 mRNA levels in lung cancer cells." (PMID 32498288, 2020). "In addition, the expression of RUNX1 increased after surgery in the peripheral blood of lung cancer patients, while the expression of RUNXOR decreased after surgery in the peripheral blood of lung cancer patients (P < 0.001)." (PMID 29914443, 2018). "Similarly, RUNX2 is also a coregulator of RUNX1, a TF of the same family, and is coexpressed in coexpression networks of unique lung cancer DEGs that are not dysregulated in other lung diseases (LCI) or in other types of cancer (LCII), with which it shares binding motifs with its target genes." (PMID 36551878, 2022).